ATG5 (autophagy related 5)
Diseases named in the same sentence as ATG5 in open-access papers (continued):
Sharing a sentence is not in itself a finding about the gene and the disease.
melanoma (continued). "To uncover the contribution of EC‐autophagy in regulating immunosurveillance in melanoma, we crossed the inducible PDGFb‐creERT2Rosa26tdTomato/tdTomatoline with Atg5fl/fl mice to delete the essential autophagy gene Atg5 from blood ECs (i.e., Atg5BECKO) upon tamoxifen administration." (PMID 38009521, 2023). "The granular expression of IFNß, a major downstream target of STING, was elevated in TECs from melanoma‐bearing Atg5BECKO mice, whereas its expression was blunted in TECs of Atg5/STINGBECDKO mice and comparable to WT TECs, functionally validating the TEC phenotype of the DKO mice." (PMID 38009521, 2023). "Moreover, ectopic expression of ATG5 inhibits the colony-forming ability of melanoma cells, whereas its downregulation can bypass oncogene-induced senescence, at least in vitro, implying that less autophagy means more transformation." (PMID 36670319, 2023). "ATG5 was able to manipulate a positive feedback loop between Wnt5a and autophagy in melanoma cells." (PMID 35194023, 2022). "Autophagy inhibition with ATG5 silencing lowered melanoma cell survival in acidic environments." (PMID 35370701, 2022). "Therefore, we decided to further investigate NRF1-mediated transcriptional regulation of ATG7 and ATG5 genes in melanoma cells." (PMID 34458153, 2021). "Moreover, inhibition of autophagy through the ATG5 (autophagy related 5) knockdown reduced melanoma cell survival in low pH conditions." (PMID 33918883, 2021). "Taken together, the migration of melanoma cells might be regulated by ATG5 and ATG7 independent on their role in autophagy." (PMID 34458153, 2021). "Furthermore, lowering ATG5 expression promoted proliferation of melanoma cells by impeding oncogene-induced senescence." (PMID 34458153, 2021). "Others have shown, however, that either pharmacological inhibition or ATG5 knockdown was insufficient to re-sensitize vemurafenib-resistant melanoma cells to this BRAFi, although higher activity of autophagy was assessed in resistant cells compared with drug-naïve counterparts." (PMID 32340261, 2020). "Furthermore, Atg5 is often decreased in primary melanomas, leading to a decrease in basal autophagy function as verified by a reduced expression of LC3." (PMID 32121322, 2020). "WNT5A overexpression leads to a significant increase in ATG5 mRNA levels in human melanoma cells." (PMID 32377431, 2020). "Interestingly, it has been demonstrated in melanoma that ATG5 downregulation is a consequence of a hypermethylation of the promoter site." (PMID 29666625, 2018). "When melanoma cells become BR cells by long-term in vitro incubation with BRAFi, c-Myc-mediated ASS1 re-expression and the levels of autophagy-associated proteins (AMPK-α1 and Atg5) are attenuated." (PMID 26771234, 2016). "Furthermore, Atg5 knockdown in human melanoma cells enhanced IL-6 production and proliferation of anti-tumorigenic CD8+IFN-γ+ and CD4+IFN-γ+ T cells." (PMID 27124579, 2016). "Inhibition of autophagy by ATG5 knockdown decreased melanoma cell survival under acidic conditions." (PMID 27583134, 2016). "Knockdown of Atg5 alone was sufficient to induce cell death in aggressive versus indolent melanomas or in pancreatic ductal adenocarcinomas, underscoring the possibility that certain tumors may rely more heavily on autophagy for survival than others." (PMID 23383069, 2013). "BRAFV600E overexpression by retroviral infection of normal human melanocytes resulted in oncogene-induced senescence (OIS), but was overcome by ATG5 silencing, suggesting that impaired autophagy may contribute to the conversion of normal melanocytes into malignant melanoma cells, at least in vitro." (PMID 34298710, 2021). "Therefore, a study demonstrated that miR-153-3p could inhibit ATG5, thus resulting in increased sensitivity of A375 and M14 melanoma cells to DTIC, and enhanced cell apoptosis and autophagy." (PMID 37304648, 2021).
melanoma (continued). "Importantly, single-copy loss of ATG5 has been identified as a distinctive feature of advanced melanomas, regardless of the mutational status of melanoma associated-oncogenes (e.g., BRAF, RAS), and associated with poor overall patient survival." (PMID 31998652, 2019). "Finally, also the in vivo autophagy-independent effects of the first-generation autophagy inhibitors, CQ/hydroxychloroquine (HCQ), should be considered, as recently evidenced in a melanoma mouse model where the key autophagy gene Atg5 was deleted either in melanoma cells or in the tumor vasculature." (PMID 27896217, 2016). "As ATG5 is often downregulated in primary melanomas 42, the association of two SNPs in this critical ATG gene with increased melanoma stage is significant as they have the potential to become new markers of melanoma risk, progression, and/or therapeutic targets." (PMID 27748080, 2016). "As it has been previously documented that individuals with scalp/neck melanomas have poorer outcomes than patients with melanomas on other sites 44, this inverse relationship warrants further studies to determine if there is a functional significance for ATG5 and this anatomic site." (PMID 27748080, 2016). "Indeed, existing reports of knockdown of the essential autophagy components Atg5 or Atg7 in the literature suggest that this approach results in increased cell death in different melanoma cell lines, although additional metabolic stressors may be required." (PMID 23383069, 2013). "Abnormal rates of autophagy and its related genes such as Atg5 and Sqstm1/p62 have been found within BRAF-mutant melanoma samples." (PMID 38732242, 2024). "We decided to search for novel TFs regulating autophagy, and specifically ATG5 and ATG7, in melanoma." (PMID 34458153, 2021). "Results from immunohistochemistry show that the expression of ATG5 and ATG7 is significantly reduced in melanoma tissues compared to benign nevi." (PMID 34458153, 2021). "Taken together, we identified NRF1 as a novel TF involved in the regulation of ATG5 and ATG7 in melanoma and therefore provide novel insights into the transcriptional regulation of autophagy." (PMID 34458153, 2021). "Another study also showed that hemizygous loss of ATG5 occurs during melanoma development, but as loss of one allele of ATG5 would not be predicted to inhibit autophagy, this raises the question whether the driver for this loss is an autophagy-independent effect of ATG5." (PMID 33664481, 2021). "Since the expression levels of ATG5 and ATG7 are reduced in melanoma tissues and their expression levels correlated with the outcome of the patients, it is important to decipher the regulatory mechanisms responsible for the observed reduction." (PMID 34458153, 2021). "The expression levels of the autophagy proteins ATG5, ATG7, ATG16L1, and two autophagic markers, LC3B and p62, were assessed in melanoma patients by immunohistochemistry." (PMID 34458153, 2021). "Knockout of ATG5 and ATG12 can reduce the colonization ability of melanoma cells in the lung and the invasion ability of gliomas, respectively." (PMID 34718338, 2021). "In the current study, we observed a significant reduction in ATG5 and ATG7 expression in primary and metastatic melanomas compared to benign nevi." (PMID 34458153, 2021). "We combined the LC3B data with an additional autophagic marker p62 and consistent with the expression of ATG5 and ATG7, we observed markedly lower LC3B and higher p62 levels in melanomas than in nevi, suggesting reduced autophagic activity in melanoma cells." (PMID 34458153, 2021). "The literature indicates that, like Beclin-1, other autophagy-related proteins, including Atg5, p62/SQSTM1 and chloroquine, which pharmacologically inhibits autophagy, also induce the expression of selected chemokines, e.g., CCL5 in melanoma cells." (PMID 34204085, 2021).
melanoma (continued). "Since our previously published and current data show decreased expression of three of the core ATGs (ATG5, ATG7 and Beclin-1) in melanoma, we decided to study the impact of NRF1 and NFE2L2 on the expression of these ATGs." (PMID 34458153, 2021). "Our results support the concept that reduced autophagic activity contributes to melanoma development and progression, and identifies NRF1 as a novel TF involved in the regulation of both ATG5 and ATG7 genes." (PMID 34458153, 2021). "With IHC staining of ATG5 and LC3 in paraffin sections derived from primary melanomas and testicular germ cell tumors, we found that both ATG5 expression and autophagy generally are downregulated in these cancer patients." (PMID 31959887, 2020). "We performed western blot analysis to examine the expressions of autophagy-related proteins and the results showed that (+)-bornyl p-coumarate induced autophagy in melanoma cells, upregulating the protein levels of Beclin-1, LC3-I, LC3-II, Atg5, Atg3 and p62." (PMID 32466337, 2020). "Downregulation of Atg5 therefore results in tumorigenesis in the early skin melanoma, and expression of Atg5 and LC3 proteins correspond with melanoma diagnosis and prognosis." (PMID 32121322, 2020). "Genetic silencing of ATG5, an autophagy regulator, by RNA interference perturbed the α-MSH-induced apoptosis in melanoma cells." (PMID 30062060, 2018). "In our experiment, autophagy was activated by CP in human melanoma cells, which was confirmed by the decreasing LC3-I/LC3-II ratio and the accumulation of Atg5/Atg12, as well as p62." (PMID 30149677, 2018). "Unexpectedly, metformin‐treated melanoma cells presented decreased levels of LC3 II/I ratio, Beclin1 and ATG5, and increased p62 in a dose‐dependent and time‐dependent manner, which indicated that metformin acted as an autophagy inhibitor in ocular melanoma cells." (PMID 35075807, 2022). "Another critical autophagy regulator ATG5 is documented to be downregulated in the early stage of melanoma, enabling the bypass of BRAF-induced senescence and contributing to the proliferation of melanoma cells." (PMID 36003368, 2022). "Interestingly, it is shown that heterozygous (but not homozygous) Atg5 loss compromised the response of BRAF inhibitors in melanoma-specific mouse models, raising caution about the incomplete blockade of this gene in clinical aspects, since this may cause an unexpected worsening of patient outcomes." (PMID 35563798, 2022). "Inhibition of melanoma autophagy through targeting at ATG5, p62/SQSTM1 and BECN1 activates MAPK8/JNK-JUN/c-Jun signaling pathway in melanoma cells which up-regulates CCL5 cytokine in the TME and thus enhance NK function via activation of NK cell activator NKp46." (PMID 36003368, 2022). "Importantly, downregulation of both ATG5 and ATG7 correlates with a less favourable outcome for patients, suggesting the potential use of ATG5 and ATG7 levels as prognostic markers in melanoma in order to recognize the more aggressive, metastatic phenotype." (PMID 34458153, 2021). "Furthermore, we identified NRF1 as a new transcription factor involved in the regulation of ATG5 and ATG7, improving our current understanding of the regulation of autophagy during melanoma development and progression." (PMID 34458153, 2021). "Moreover, consistent with the reduced levels of ATG5 and ATG7, we found changes in the expression of autophagic activity markers, indicating reduced autophagy in melanomas as compared to benign nevi." (PMID 34458153, 2021).
melanoma (continued). "In addition, we determined the expression of stress (CHOP, XBP1, and BIP) and autophagy (DRAM1, P62, ATG5, and ATG7) marker genes; furthermore, we successfully developed an HA15-resistant melanoma cell line." (PMID 33498201, 2021). "On the other hand, silencing of NRF1 could, in addition to the expression of ATG5 and ATG7, target several other genes, which could positively or negatively influence the migration potential of melanoma cells." (PMID 34458153, 2021). "Our results showed that the expression of LC3 and ATG5 mRNA was significantly increased in B16 melanoma cells treated by the CAP, whereas CAP-treated non-malignant L929 cells showed an appreciable reduction in the expression of autophagic-related genes." (PMID 32650505, 2020). "The autophagy gene ATG5 is expressed at reduced levels in melanoma but not in benign melanocytes in nevi." (PMID 31417903, 2019). "Among them, we found several autophagy-related genes such as AMBRA1, ATG5, ATG12, ATG13 and ATG4B, which could be potentially downregulated in BRAFi-resistant melanoma cells." (PMID 30254376, 2019). "Interestingly, inhibition of autophagy by 3-MA or blocking ATG5 expression was enough to retard α-MSH-induced apoptosis, but autophagy-inducer rapamycin treatment contrarily increased the apoptosis of melanoma cells during hypoxia." (PMID 30062060, 2018). "Indeed, the presence of Cx43 at the IS could be restored in hypoxic melanoma/NK cell cocultures by inhibiting hypoxia-induced autophagy flux by hydroxychloroquine or the hypoxia-induced autophagosome formation by 3-methyladenine or knock down of the ATG5 gene in hypoxic melanoma cells." (PMID 28919895, 2017). "In addition to BECN1 inhibition, targeting other autophagy-related molecules, such as ATG5 or p62/SQSTM1, or inhibiting melanoma autophagy pharmacologically by chloroquine can similarly induce the expression of CCL5 in melanoma cells and consequently enhance the antitumor capacity of NK cells." (PMID 36003368, 2022). "Moreover, increased expressions of beclin-1, Atg3, Atg5, p62, LC3-I and LC3-II proteins and suppression by autophagic inhibitor 3-methyladenine (3-MA), indicated that (+)-bornyl p-coumarate triggered autophagy in the melanoma cells." (PMID 32466337, 2020). "In addition, Western blotting assay also indicated that SMI-4a enhanced the protein levels of Atg5, LC3-II and Beclin1 in a dose-dependent manner in melanoma cells, indicating that SMI-4a could induce autophagy in melanoma cells." (PMID 29483938, 2018). "The authors found that inhibiting autophagy in vemurafenib-resistant melanomas either by ATG5 knockdown or pharmaceutically was not sufficient in restoring sensitivity to vemurafenib treatment; however, combination of autophagy inhibition and MEK inhibition increased melanoma cell death." (PMID 27583134, 2016). "Moreover, the finding of significantly increased expression levels of the Atg5-12 complex and beclin-1 beginning after 24 h of incubation provided additional strong evidence supporting the hypothesis that IMQ combined with IR induced autophagy in mouse melanoma cells." (PMID 28212561, 2017).
lung carcinoma (51 papers, 2015 to 2025). "More recently, systemic autophagy inhibition through Atg5 knockdown significantly reduced established tumor growth, which is associated with defective glucose and lactate uptake in Kras-driven lung cancer mice." (PMID 38067169, 2023). "For example, the incidence of Kras-driven lung cancer is significantly increased in ATG5-deficient mice." (PMID 35529455, 2022). "High autophagy activity (high ATG5 expression) and high Zeb1 expression are correlated and associated with poor clinical outcomes in human lung cancer." (PMID 33468994, 2021). "We showed that sensitivity to cisplatin was potentiated by ATG5 knockdown, indicating that autophagy activation is associated with acquired cisplatin resistance in lung cancer." (PMID 28945807, 2017). "Inactivation of autophagy, by specific silencing of BECN1 or ATG5, restored lung cancer cell sensitivity to T cells lysis, which was associated with a decrease in hypoxia-induced pSTAT3." (PMID 27917371, 2016). "Augmented induction of autophagy by hypoxia decreased lung cancer cell susceptibility to cisplatin-induced apoptosis and inhibited autophagy by 3-MA or siRNA targeted ATG5 effectively attenuated cisplatin resistance under hypoxia." (PMID 27043621, 2016). "Inactivation of Atg5-dependent autophagy increased the number of tumor foci and favored the progression from hyperplasia to adenoma in a murine model of lung cancer (with KrasG12D mutation)." (PMID 27917371, 2016). "Beclin-1 is deleted in 40- 75% of cases of humansporadic breast, ovarian, and prostate cancers.Knocking down ATG5 and beclin-1, two knownessential autophagic molecules, can cause radiationresistance among lung cancer cells." (PMID 25780525, 2015). "In an oncogenic kRas-driven lung cancer mouse model, Atg5 deficiency is associated with an increase in the numbers of early hyperplastic foci and regulatory T cells, and then further antibody treatment or depletion of FoxP3+ cells decrease the hyperplastic lesions to those seen in the controls." (PMID 38067169, 2023). "Likewise, deficiency of ATG5 effectively leads to tumorigenesis of liver and lung cancer in a mouse model." (PMID 37138798, 2023). "For instance, upregulation of ATG5 depresses the sensitivity of prostate and lung cancer cells to chemotherapy by inducing autophagy, whereas silencing of ATG5 suppresses autophagy and increases the sensitivity to imatinib mesylate." (PMID 41282485, 2025). "In lung cancer, ATG5 has been found to regulate malignant cell phenotypes, with high expression in lung squamous cell carcinoma tissues, and its silencing leads to autophagy suppression in these cells." (PMID 39735666, 2025). "Another recent study revealed the involvement of Plasmacytoma Variant Translocation 1 (PVT1), a long non-coding RNA, in regulating autophagy through the miR-140-3p/ATG5 axis in lung cancer development." (PMID 39735666, 2025). "Autophagy, a key cellular process, is tightly linked to cancer development; genes like ATG5 and ATG10 influence lung cancer progression, and epigenetic regulators modulate autophagy-related carcinogenesis." (PMID 40832611, 2025). "The results indicated that the expression of ATG7 and ATG5 proteins was elevated in lung cancer cells treated with SM-3 compared to those treated with Res." (PMID 40287470, 2025). "For example, low ATG5 expression reduces cell growth in RAS mutant lung cancer cell lines.ATG10 overexpression was associated with poor prognosis in lung cancer." (PMID 40832611, 2025). "Within autophagy, macroautophagy is regulated by a set of autophagy-related (ATG) proteins, and previous studies have highlighted the significance of ATG5-mediated autophagy in lung cancer progression." (PMID 39735666, 2025). "This reduction was accompanied by significantly decreased levels of Beclin 1, ATG7, and ATG5, along with an increased level of p62/SQSMT1 in PC-9GR (T790M mutated lung cancer) cells." (PMID 39272847, 2024).